EGFR (epidermal growth factor receptor)
Diseases named in the same sentence as EGFR in open-access papers (continued):
Sharing a sentence is not in itself a finding about the gene and the disease.
lung adenocarcinoma (continued). "Approximately 50% of Asian patients with lung adenocarcinoma have EGFR-activating mutations, mainly including exon 19 base deletions (Del19) and point mutation in exon 21 (L858R)." (PMID 36744262, 2023). "As a predominant cancer-driving genetic variant in lung adenocarcinoma, the prognostic impact of EGFR mutation has been discussed." (PMID 36918771, 2023). "Specific mutations in the EGFR tyrosine kinase domain sensitize lung adenocarcinoma tumors to respond differentially to EGFR tyrosine kinase inhibitors (TKIs)." (PMID 37190191, 2023). "The difference in the prognosis of early-stage operable lung adenocarcinoma between EGFR mutation and wild-type patient groups was inconclusive in previous studies." (PMID 36766495, 2023). "Regarding the use of EGFR inhibitors, such an approach would be of limited use regarding potential prevention trials, particularly in Caucasian smokers, since few of these lung adenocarcinomas have EGFR mutations." (PMID 37169023, 2023). "Accurately identifying EGFR mutation status in lung adenocarcinoma patients can greatly improve patient prognosis." (PMID 37014500, 2023). "While EGFR mutations were detected in 51 tissue samples from 80 patients with stage III or IV lung adenocarcinoma, they showed concordant results in 33 (65.0%) of the liquid biopsy samples taken from these cases." (PMID 38304031, 2023). "The efficacy of bevacizumab in combination with erlotinib or afatinib for the treatment of untreated advanced EGFR-mutated lung adenocarcinoma has been explored in several previous pivotal clinical trials and clinical studies." (PMID 37854677, 2023). "For lung adenocarcinoma with EGFR 19Del, L858R mutation, the Observation group showed a better ORR, mPFS and 2-year survival than the Control group." (PMID 37390279, 2023). "This is consistent with multi-institutional retrospective data showing the efficacy of tyrosine kinase inhibitors in patients with EGFR-mutated lung adenocarcinoma with brain metastases." (PMID 37201304, 2023). "Last, we trained a multiple-instance learning model that achieves state-of-the-art performance for predicting EGFR mutational status in lung adenocarcinoma resections and investigated the features learned by the model." (PMID 36927889, 2023). "This review aimed to summarize the research progress on 18F-FDG PET/CT radiomics for predicting EGFR mutation status and subtypes in lung adenocarcinoma." (PMID 38094613, 2023). "Osimertinib, a third-generation EGFR TKI, targets mutant EGFR harboring both TKI-sensitizing and first/second-generation EGFR TKI-resistant T790M mutation in lung adenocarcinoma patients." (PMID 37190191, 2023). "Studies have shown that EGFR TKIs effectively prolong the progression-free survival (PFS) of lung adenocarcinoma patients with EGFR mutations." (PMID 36983578, 2023). "SUVmax had a weak predictive ability for EGFR mutation status in lung adenocarcinoma (training set AUC = 0.582, 95% CI 0.526–0.638, testing set AUC = 0.584, 95% C0I 0.475–0.694)." (PMID 37014500, 2023). "In this study, we retrospectively enrolled patients with lung adenocarcinomas harboring susceptible EGFR mutations, who were diagnosed and treated with first-line afatinib in three Kaohsiung Medical University-affiliated hospitals." (PMID 37046679, 2023). "Studies have shown that tyrosine kinase inhibitors (TKIs) can effectively prolong the progression-free survival (PFS) of patients with EGFR mutations, and therefore they are widely used in the targeted therapy for lung adenocarcinoma." (PMID 37014500, 2023). "Several studies have demonstrated that the frequency of driver mutations in lung adenocarcinoma varies by race and ethnicity, with EGFR mutations being the most prevalent in Asian patients." (PMID 37737544, 2023).
lung adenocarcinoma (continued). "Taken together, these results support the deregulation of arginine synthesis after HSP90 inhibition as a key mechanism with the potential to block cell proliferation in lung adenocarcinoma with mutated EGFR or EML4-ALK translocation." (PMID 37762133, 2023). "Studies on applying 18F-FDG PET/CT MLR in predicting EGFR mutations in patients with lung adenocarcinoma." (PMID 38094613, 2023). "EGFR mutation was examined in 135 patients, and 85 (63.0%) patients had EGFR mutated lung adenocarcinoma." (PMID 37105937, 2023). "In our previous experience, the survival curve of Sardinian lung adenocarcinoma patients carrying even very low rates (≤1.5%) of EGFR-T790M variants at baseline was significantly poorer in comparison to that of cases without such a mutation." (PMID 37047382, 2023). "Pathway analysis showed that miR-502-3p, miR-500a-3p, and miR-652-3p (two other upregulated miRNAs in EGFR-mutated lung adenocarcinoma), interact with and downregulate MUC4." (PMID 37111289, 2023). "Gefitinib served as a first-generation EGFR-TKI, and compared with traditional chemotherapy, the drug significantly prolonged the survival of patients with lung adenocarcinoma harboring the EGFR-sensitizing mutation." (PMID 38328605, 2023). "Met amplification is 1–3% in lung adenocarcinoma and reaches 20% in the case of concomitant EGFR mutation." (PMID 38072918, 2023). "In patients with lung adenocarcinoma, epidermal growth factor receptor (EGFR) mutations are present in 10%–20% of Caucasian and in 40%–60% of South-East Asian population." (PMID 37284196, 2023). "A patient with multi-line treatment of stage IV lung adenocarcinoma who developed the EGFR G724S resistance mutation after receiving osimertinib was repeatedly evaluated as being in PR after receiving afatinib, and the PFS was more than 9 months." (PMID 37366888, 2023). "Radiomics extracted from peritumoral region can add extra value in predicting EGFR mutation status of lung adenocarcinoma patients, with the optimal peritumoral range of 4 mm." (PMID 37749461, 2023). "Fortunately, the advancement of EGFR-TKIs dramatically revolutionized treatment strategies for a great proportion of NSCLC patients carrying EGFR mutations, which is the most common oncogenic mutations among Asians with lung adenocarcinoma (LUAD)." (PMID 37189759, 2023). "T790M mutation has also been detected in a small number of untreated lung adenocarcinoma, known as primary T790M mutation, accounting for about 1% of EGFR-mutated lung adenocarcinoma." (PMID 37697337, 2023). "This study investigated the association between PET/CT-derived SUVmax and EGFR mutation status in 366 patients with lung adenocarcinoma." (PMID 36983578, 2023). "Although epidermal growth factor receptor (EGFR) mutation is common in primary lung adenocarcinoma, it is rarely reported in PEAC." (PMID 36212391, 2022). "A 91-year-old man was diagnosed with lung adenocarcinoma harboring an EGFR L858R mutation and was started on osimertinib." (PMID 36081968, 2022). "EGFR mutations are frequently reported to correlate with estrogen receptor (ER) α and/or β-expressions in lung adenocarcinoma." (PMID 35664735, 2022). "Patients who underwent curative surgery for Mt (n = 208) harboring the EGFR exon 21 L858R point mutation or EGFR exon 19 deletion mutation and EGFR mutation wild-type lung adenocarcinoma (Wt, n = 358) between January 2010 and December 2020 were included." (PMID 36085020, 2022).
lung adenocarcinoma (continued). "Our study demonstrated that the EGFR Q787Q polymorphism is a prognostic factor for EGFR-mutated lung adenocarcinoma treated with TKIs." (PMID 35387120, 2022). "Eligible studies were of an experimental or observational design that included lung adenocarcinoma patients with confirmed EGFR exon mutations (21 and 19) and associated clinical characteristics and CT imaging patterns." (PMID 35774697, 2022). "Epidermal growth factor receptor (EGFR) mutations are detected in approximately 30% of all lung adenocarcinomas, and the most common EGFR mutation occurring in ∼50% of patients is termed “exon 19 deletion” (ex19del)." (PMID 35867821, 2022). "With computed tomography of lung adenocarcinoma, it is already possible to link mutational status (EGFR, KRAS, and ALK) with imaging-assessed characteristics, such as lymphangitis, pleural effusion, or lung metastases." (PMID 35884409, 2022). "A total of 137 lung adenocarcinoma patients with EGFR-activating mutations identified from baseline tumor biopsies using a routine cobas EGFR Mutation Test were enrolled in this study." (PMID 36232650, 2022). "Lung adenocarcinoma patients with EGFR mutations have a higher incidence of BM, both at initial diagnosis and during the course of the disease, usually leading to poor quality of life and survival prognosis, even after treatment with TKIs." (PMID 35241046, 2022). "Epidermal growth factor receptor (EGFR)-tyrosine kinase inhibitors (TKIs) have a good clinical efficacy in lung adenocarcinoma harboring activating-mutation EGFR." (PMID 35664735, 2022). "In this study, we retrospectively collected a relatively large data set and constructed a model based on CT radiomics signature to noninvasively predict the mutation status of EGFR molecular subtype in lung adenocarcinoma." (PMID 35574401, 2022). "In contrast, the EGFR mutation rate was reported only 11% in US and European patients of lung adenocarcinoma." (PMID 35230491, 2022). "The second case follows a patient diagnosed with lung adenocarcinoma with multiple metastases (cT2N0M1, stage IV, L858R mutation in exon 21 of EGFR) in February of 2018." (PMID 35943592, 2022). "EGFR mutations are the most common target driver mutations found in lung adenocarcinoma and are detected in 62% of the Asian population." (PMID 36230708, 2022). "An approximately 30% of advanced lung adenocarcinoma (LUAD) patients with epidermal growth factor receptor (EGFR) mutations benefit from treatment with EGFR tyrosine kinase inhibitors (TKIs)." (PMID 34675407, 2022). "The EGFR mutation rate is as high as 51.4% in Asian patients with lung adenocarcinoma, making it particularly important to optimize the treatment protocol for NSCLC with EGFR mutations." (PMID 36172729, 2022). "In conclusion, our preoperative CT-based deep learning model was able to predict EGFR mutations in patients with lung adenocarcinomas manifesting as pGGN." (PMID 36119545, 2022). "There was a positive correlation between EGFR expression and genes associated with mAChRs in lung adenocarcinoma (LUAD) and lung squamous cell carcinoma (LUSC) patients." (PMID 35565451, 2022). "There is also tight correlation between radiotherapy and immune status, and brain metastases (BM) radiotherapy is an important treatment in patients with BM from lung adenocarcinoma harboring epidermal growth factor receptor (EGFR) mutations." (PMID 35241046, 2022). "Important drug for the treatment of patients with EGFR-mutated lung adenocarcinoma is EGFR-tyrosine kinase inhibitors (TKI)." (PMID 35935969, 2022). "PFS was not longer in the osimertinib plus bevacizumab group than in the osimertinib group in patients with advanced lung adenocarcinoma with EGFR T790M mutation." (PMID 36508072, 2022). "The integrated model outperformed the TNM system and allowed further stratification of survival outcomes into three risk groups of patients with advanced EGFR-mutated lung adenocarcinoma." (PMID 35053473, 2022).
lung adenocarcinoma (continued). "Concurrent use of PPIs with first-line gefitinib or erlotinib therapy was associated with a worse OS and TTNT in patients with lung adenocarcinoma harboring EGFR mutations." (PMID 35488047, 2022). "Epidermal growth factor receptor (EGFR)-tyrosine kinase inhibitor (TKI) has a good clinical efficacy in lung adenocarcinoma harboring some types of gene mutation in the tyrosine kinase domain of EGFR." (PMID 35664735, 2022). "This study aimed to investigate the frequency and types of EGFR gene mutations among Iranian patients with lung adenocarcinoma referred to a specialized lung diseases hospital from 2014 to 2019." (PMID 35463723, 2022). "Deep learning approach of CT images combined with clinical factors can predict EGFR mutations in patients with lung adenocarcinomas manifesting as pGGN, and its clinical utility was demonstrated in a real-world sample." (PMID 36119545, 2022). "One hundred and five patients with advanced EGFR-mutated lung adenocarcinoma treated with TKIs were retrospectively analyzed." (PMID 35053473, 2022). "Here, we reported an EGFR-mutation-positive lung adenocarcinoma patient who was admitted to a hospital for cough and chest distress accompanied by shortness of breath." (PMID 36110968, 2022). "This case report and literature review highlighted the importance of confirming the genetic profile of EGFR mutated lung adenocarcinoma showing SQ transformation as resistance to EGFR TKI, and treatment with individualized EGFR TKI doses." (PMID 35960133, 2022). "In this study, the radiomics model achieved an AUC of 0.64, which was inferior to those of existing radiomics studies predicting EGFR mutation for lung adenocarcinoma." (PMID 36119545, 2022). "This patient was diagnosed with lung adenocarcinoma and bone metastasis (cT2N1M1, stage IV, L858R mutation in EGFR exon 21) and was treated accordingly with icotinib." (PMID 35943592, 2022). "The remarkable success of EGFR‐TKIs for the treatment of lung adenocarcinoma patients with advanced‐mutated EGFR has been undermined by the invariable development of acquired resistance to these drugs." (PMID 35593080, 2022). "Associations of GRSs with PFS and OS of advanced lung adenocarcinoma patients treated with EGFR-TKIs." (PMID 35372081, 2022). "Approximately 70% of lung adenocarcinoma patients harboring EGFR-mutated develop resistance against TKI therapy, and cancer eventually progresses during treatment within the next year." (PMID 35330404, 2022). "LncRNA LINC00460 overexpression in EGFR-mutant lung adenocarcinoma was reported to be associated with poorer response to EGFR TKI therapies." (PMID 35209919, 2022). "In lung adenocarcinoma, oncogenic EGFR expression and mutations co‐occur with many other oncogene alterations." (PMID 35014181, 2022). "In lung adenocarcinoma, EGFR mutation has a predominance that ranges from 10% to 78% and vary significantly depending on ethnic origin and geographic location." (PMID 35954442, 2022). "The overall survival (OS) of patients with unresectable EGFR mutation lung adenocarcinoma (Mt) has dramatically improved to 30–50 months with EGFR-TKI." (PMID 36085020, 2022). "Patients with adenocarcinoma of the lung who also had scar cancer or old pulmonary tuberculosis lesions were shown to have a higher probability of harboring EGFR mutations, particularly exon 19 deletions." (PMID 35806042, 2022). "In conclusion, this study showed the real-world experience of EGFR-TKI use as a first-line treatment in EGFR-mutated lung adenocarcinoma patients with poor PS." (PMID 35158940, 2022). "We performed RNA-seq and EGFR driver gene mutation detection in the tumor microenvironment of lung adenocarcinoma before and after EGFR-TKI administration." (PMID 36505794, 2022).
lung adenocarcinoma (continued). "Pathological stage IB-IIIA lung adenocarcinoma with an epidermal growth factor receptor (EGFR) mutation (Mt) has a high recurrence rate even after complete resection." (PMID 36085020, 2022). "Lee believed that the presence of EGFR activating mutations should be used as an indicator of prognosis in patients with lung adenocarcinoma and brain metastases." (PMID 35477385, 2022). "Associations of SNPs and GRS with OS and PFS of advanced lung adenocarcinoma patients treated with EGFR-TKI stratified by sex." (PMID 35372081, 2022). "Low SUVmax of the distant metastasis was beneficial to the existence of EGFR mutations in advanced lung adenocarcinoma." (PMID 35515138, 2022). "We found that ASC of lung has similar genetic abnormalities as those of adenocarcinoma of the lung, with about a third of the cases harboring an EGFR mutation." (PMID 35871081, 2022). "A total of 14,647 adult patients were identified with newly diagnosed EGFR mutation-positive stage IIIB/IV lung adenocarcinoma between Jan 2011 and Dec 2016." (PMID 35488047, 2022). "EGFR mutation was significantly associated with poor RFS of stage I lung adenocarcinoma only in cases with high-grade patterns." (PMID 35266536, 2022). "For instance, osimertinib, a third-generation tyrosine kinase inhibitor, prolonged progression-free survival (PFS) to 18.9 months in patients with lung adenocarcinoma with the epidermal growth factor receptor (EGFR) common mutation." (PMID 35954337, 2022). "Epidermal growth factor receptor (EGFR) mutations are the most common oncogenic driver mutations in lung adenocarcinomas." (PMID 35266536, 2022). "A re-biopsy revealed a poorly differentiated lung adenocarcinoma together with EGFR p.L858R mutation." (PMID 35273908, 2022). "Epidermal Growth Factor Receptor (EGFR) mutations in lung adenocarcinoma have been previously associated with specific clinical characteristics and Computed Tomography (CT) patterns." (PMID 35774697, 2022). "Epidermal growth factor receptor tyrosine kinase inhibitors (EGFR-TKIs) are standard treatments in patients with EGFR-mutated lung adenocarcinoma." (PMID 35158940, 2022). "While T790M mutation occurs in less than 5% of untreated EGFR mutant lung adenocarcinomas, about 50%–70% of the EGFR mutated tumors develop T790M mutation as an acquired resistance if treated with first-generation TKIs." (PMID 36277960, 2022). "EGFR mutation at the kinase domain, which leads to constitutional EGFR activation, is one of the major genetic defects found in lung adenocarcinoma." (PMID 35705979, 2022). "Elevated serum CEA levels predicted the presence of EGFR mutations not only in primary lung adenocarcinoma patients, but also in patients with recurrent lung adenocarcinomas." (PMID 35624472, 2022). "Tyrosine Kinase Inhibitors (TKIs) against mutations of the EGFR gene were the first to introduce survival benefits in patients with lung adenocarcinoma, opening a new era in this setting." (PMID 35012520, 2022). "Roughly 20% of lung adenocarcinoma patients in western countries carry genetic alterations in EGFR, while 40%–60% of patients in East Asia are EGFR mutation positive." (PMID 34766737, 2022). "Despite not being performed routinely in clinical practice, 20 patients diagnosed with lung adenocarcinoma with an initial tissue mutation in the EGFR gene were also followed up to fine-tune this technique." (PMID 36497340, 2022). "We sought to characterize the genomic landscape associated with CDKN2A deletion in EGFR/ALK- lung adenocarcinoma specimens using the Foundation Medicine genomic dataset." (PMID 35739333, 2022). "This case report describes a female patient who presented with a metastatic hepatic rupture and was subsequently diagnosed with EGFR-mutated lung adenocarcinoma." (PMID 35433405, 2022). "In lung adenocarcinoma, activating EGFR gene mutations have been identified as the main oncogenic factors, especially in Asian countries." (PMID 36438567, 2022).